NGF (nerve growth factor)
Diseases named in the same sentence as NGF in open-access papers (continued):
Sharing a sentence is not in itself a finding about the gene and the disease.
diabetic encephalopathy (3 papers, 2021 to 2025). A brain disease that is characterized by functional impairment of cognition, cerebral signal conduction, neurotransmission and synaptic plasticity, and underlying structural pathology associated with diabetes. "NGF also counteracts molecular alterations, while administration of NGF reduces ER stress and apoptosis in Schwann cells in diabetic peripheral neuropathy, also effectively lessening neuronal death induced by glucose fluctuation in diabetic encephalopathy." (PMID 37373824, 2023). "We also aimed to verify the neuroprotective potential of the two types of CNTs, delivering them in rats affected by early diabetic encephalopathy and analysing the modulation of nerve growth factor metabolism and the effects of CNTs on the neuronal and glial phenotypes." (PMID 36131737, 2021).
Follicular Cyst (3 papers, 2010 to 2021). Cyst due to the occlusion of the duct of a follicle or small gland. "Studies in the rat have shown that the abnormally elevated production of NGF within the ovary increases androgen secretion, disrupts the estrous cycle and is sufficient to initiate several of the structural and functional alterations associated with the development of follicular cysts." (PMID 29580253, 2018). "In vivo NGF led to an anovulatory condition with the appearance of follicular cysts and decreased number of corpora lutea (corresponding to noradrenergic activation)." (PMID 33716987, 2021). "Research has shown that transgenic mice expressing excessive NGF exhibit PCOS-like symptoms, such as the formation of follicular cysts, hyper-androgenemia, increased granulosa cell apoptosis, reduced ovulation and fertility and perturbed reproductive and metabolic features." (PMID 29580253, 2018).
head and neck cancer (3 papers, 2022 to 2025). A primary or metastatic malignant neoplasm affecting the head and neck. "The cellular components synthesise growth factors such as EGF, TGFα and β, VEGF, and NGF, which have been shown to initiate paracrine signalling in head and neck cancer cells by binding to cell surface receptors." (PMID 35681586, 2022). "This review provides evidence that when Akt, a signalling protein, is activated by different growth factors such as epidermal growth factor, transforming growth factor α/β, vascular endothelial growth factor and nerve growth factor, head and neck cancer cell spreading is stimulated." (PMID 35681586, 2022).
hematoma (3 papers, 2011 to 2025). A hematoma is a collection of blood from a vascular structure into an extravascular space. "Its role in supporting epithelial survival and repair is reflected in important pathways such as “Hematoma Resolution Signaling” and “NGF-stimulated Transcription”." (PMID 40649959, 2025). "A large number of NGF-positive cells were detected around the hematoma, increased with ICH time, and peaked at 7 days in the ICH control group and ICH intervention group." (PMID 23554704, 2011). "In the pepsin + amprenavir vs. sham comparison, the top canonical pathways included Hematoma Resolution Signaling, rRNA Processing, and NGF-stimulated Transcription, while Oxidative Phosphorylation, Mitochondrial Dysfunction, and rRNA Processing were prominent in the pepsin alone comparison." (PMID 40649959, 2025). "In conclusion, HBO improves consciousness, cognitive function, and prognosis in patients with severe or moderate TBI through decreasing TBI-induced hematoma volumes, promoting the recovery of EEG rhythms, and modulating the expression of serum NSE, S100β, GFAP, BDNF, NGF, and VEGF." (PMID 36034283, 2022). "HBO may be an effective treatment for patients with TBI to improve consciousness, cognitive function and prognosis through decreasing TBI-induced hematoma volumes, promoting the recovery of EEG rhythm, and modulating the expression of serum NSE, S100β, GFAP, BDNF, NGF, and VEGF." (PMID 36034283, 2022).
herpetic keratitis (3 papers, 2007 to 2025). "Murine NGF has been proposed as a potential therapy to treat and prevent the recurrence of herpetic keratitis." (PMID 40649793, 2025). "For herpetic keratitis in rabbits, topical treatment with NGF helped reduce intensities of effects relative to acyclovir." (PMID 36430547, 2022). "We recommend that trials of NGF therapy in herpetic keratitis should be carried out on a larger number of acyclovir resistant cases." (PMID 17974026, 2007). "Although the molecular mechanisms underlying NGF’s protective effects in herpetic keratitis are not yet fully understood, emerging evidence suggests that its therapeutic benefits arise from its immunomodulatory, anti-inflammatory, and neurotrophic properties rather than direct antiviral activity." (PMID 40649793, 2025).
hyperandrogenism (3 papers, 2015 to 2023). Excessive secretion of androgens from the adrenal glands or gonads. "In females, high NGF production has been linked to hyperandrogenism, along with reproductive and metabolic dysregulation." (PMID 36768281, 2023). "Studies suggest that women with PCOS have elevated levels of NGF (nerve growth factor), which is required for ovarian follicular growth, and that this increase is induced by hyperandrogenism and elevated plasma LH concentrations." (PMID 25763280, 2015).
hypogonadism (3 papers, 2022 to 2024). A disorder characterized by decreased function of the gonads. "NGF administration appears promising as an alternative treatment for hypogonadism and as a protective measure against gonadal damage from chemotherapy." (PMID 38792459, 2024). "In particular, recent studies suggest NGF modulation could be beneficial for conditions such as Partial Androgen Deficiency of the Aging Male (PADAM), hypogonadism, and gonadal dysfunction induced by cancer treatments." (PMID 38792459, 2024). "A further alternative therapeutic option for hypogonadism treatment might be represented by NGF administration." (PMID 36361912, 2022).
inflammatory bowel disease (3 papers, 2008 to 2025). A spectrum of small and large bowel inflammatory diseases of unknown etiology. "Numerous lines of evidence indicate that NGF is implicated in the pathogenesis of pain resulting from various conditions, such as osteosarcoma (OSA), feline idiopathic cystitis (FIC), chronic inflammatory bowel disease (IBD), and neuropathies." (PMID 41301953, 2025).
inflammatory skin disease (3 papers, 2019 to 2022). Inflammatory skin disorders covers a broad category that includes many conditions ranging in severity, from mild itching to grave medical health complications These disorders are common in people of all ages and races. "Nerve growth factor (NGF), a neurotrophin, is involved in a variety of inflammatory skin disorders, such as AD and prurigo nodularis, which usually present with pruritus and hyperalgesia." (PMID 36012289, 2022). "For instance, IL-1β, IFN-γ, and IL-4 were found to regulate NGF and BDNF expression in human culture bronchial smooth muscle cells whereas NGF was significantly increased in keratinocytes during different skin inflammatory diseases, with TNF-α probably mediating this effect." (PMID 31616373, 2019).
intrauterine growth restriction (3 papers, 2021 to 2025). "Notably, lower NGF levels have been observed in the infants of diabetic mothers, particularly those with intrauterine growth restriction (IUGR), suggesting that maternal diabetes may impair fetal neurodevelopment through altered NGF dynamics." (PMID 40284249, 2025). "Intrauterine growth restricted (IUGR) cases are characterized by intrauterine hypoxia, and NGF decreased significantly in the IUGR group compared with the fetus at the appropriate gestational age." (PMID 34759794, 2021).
joint disease (3 papers, 2019 to 2026). "With anti-NGF antibodies causing serious adverse events observed in clinical trials, this study was performed to investigate the effects of systemic anti-NGF treatment in a rabbit model of surgically induced joint instability." (PMID 37435308, 2023). "The purpose of the current study was to evaluate the effects of systemic anti-NGF treatment in a rabbit model of surgically induced joint instability, focusing on structural readouts like subchondral bone and cartilage and behavioral measures." (PMID 37435308, 2023). "The aim of this study was to investigate effects of systemic anti-NGF-treatment on structure and symptoms in rabbits with surgically induced joint instability." (PMID 37435308, 2023). "Mast cells play a central role in SP-mediated nociception and inflammation in joint diseases, as upon activation, they release granules containing histamine, serotonin, proteases, and trophic factors such as NGF, which contribute to pain sensitization and joint damage." (PMID 41608074, 2026).
keloid (3 papers, 2020 to 2023). An irregularly shaped, elevated mark on the skin caused by deposits of excessive amounts of collagen during wound healing. "Mast cells in the dermis in keloids produce large amounts of histamine, nerve growth factor (NGF), and serine proteases, which facilitate fibroblasts to produce more collagen." (PMID 37692181, 2023). "Likewise, NGF in keloids stimulates histamine production by keratinocytes, creating a closed loop that leads to itching and inflammation." (PMID 37692181, 2023). "Gene expression for nerve growth factor (NGF) and TGF-β1 was considerably elevated in keloids when compared to normal skin." (PMID 36483731, 2022).
latent infection (3 papers, 2009 to 2020). "For example, LUHMES cells require an initial treatment with acyclovir for the first 48 h of infection, PC-12 cells need to be differentiated with nerve growth factor (NGF) first in order to support HSV-1 latent infection." (PMID 32245260, 2020). "Studies indicated that PI3K activation by nerve growth factor (NGF) interaction with its high-affinity tropomyosin receptor kinase (TrkA) generated a cascade of signals resulting in neuronal gene expression changes thus promoting latent infection." (PMID 28344765, 2017). "This hypothesis may also have important translational implications, as the selective molecular targeting of NGF during latent infections would become critical for the management of the chronic sequelae of RSV infection by improving the efficiency of viral clearance." (PMID 19649262, 2009).
melasma (3 papers, 2021 to 2025). "Similarly, ET-1 in SL, HGF in DF /SL, KGF in SL /melasma, IL-1α in SL, sFRP-2 in SL /melasma, and NGF in melasma stimulate melanogenesis of human melanocytes." (PMID 38674144, 2024).
myeloma (3 papers, 2007 to 2019). "With the observation that the decreasing tendency of △NGF in the CIPN group was shown in multiple myeloma than other diseases, we considered that the chemotherapeutic drugs for multiple myeloma, such as bortezomib or thalidomide, could cause NGF-dependent CIPN." (PMID 28827818, 2017). "We provide important insights into the mechanisms underlying the control of pain-related factors in myeloma, and suggest that targeted therapeutics to combat microenvironmental induction of pain-related factors such as NGF warrant further study in multiple myeloma." (PMID 31578352, 2019). "Also, in newly diagnosed multiple myeloma patients, the depletion of NGF was more prominent." (PMID 28827818, 2017). "Moreover, we exploited the resistance of myeloma plasma cells to retroviral transduction by targeting the hematopoietic CD34+ cell population with a retroviral vector carrying a selectable marker (the truncated form of the human receptor for nerve growth factor, ΔNGFR)." (PMID 17626627, 2007). "The NGF receptors TrkA (encoded by NTRK1) and p75NTR (encoded by NGFR) were not strongly or consistently expressed by MM cell lines, which was consistent with a lack of effect of recombinant NGF on myeloma cell growth." (PMID 31578352, 2019). "When we focused on the patients with newly diagnosed multiple myeloma (n = 8 for no-CIPN and 11 for CIPN), the NGF levels were significantly decreased in the CIPN group (△NGF = +2.52 ± 8.39 pg/ml for No-CIPN and −4.14 ± 4.87 pg/ml for CIPN; p-value = 0.043)." (PMID 28827818, 2017).
neuroendocrine neoplasm (3 papers, 2021 to 2025). Endocrine tumors, also referred to as neuroendocrine tumors (NETs), are defined by a common phenotype which is characterized by the expression of general markers (neuron specific enolase, chromogranin, synaptophysin) and hormone secretion products. "In addition, the NGF signaling known to be implicated in neuroendocrine neoplasms, includes some of the most frequently mutated genes in our casuistry." (PMID 35794609, 2022).
ocular hypertension (3 papers, 2004 to 2024). Abnormally high intraocular pressure. "Topical application of NGF preserved RGCs and their axons in a model of ocular hypertension." (PMID 39458902, 2024).
oral squamous cell carcinoma (3 papers, 2022 to 2024). "Oral squamous cell carcinoma cells secrete nerve growth factor (NGF), a known regulator of TRPV1 expression." (PMID 38339399, 2024). "Few studies demonstrated a strong association between NGF and TrKA and PNI in oral squamous cell carcinoma." (PMID 37431326, 2023).
overactive bladder syndrome (3 papers, 2022 to 2025). "Increased levels of NGF correlate with overactive bladder syndrome, indicating that NGF is an important factor in bladder physiology." (PMID 36835106, 2023). "Women with overactive bladder syndrome (OAB) have a lower urinary ratio of nerve growth factor (NGF) to its precursor (proNGF) compared to healthy controls." (PMID 36144224, 2022).
prostate tumor (3 papers, 2014 to 2024). "Given the responses to prostate tumors, it is reasonable to assume that the NGF may also induce neuroendocrine differentiation of adenocarcinomas after ADT, which may affect tumor growth and progression in the tumor microenvironment." (PMID 33398073, 2021). "A previous study revealed that NGF could prevent prostate tumor growth through an indirect effect, possibly innervation of the tumor neovasculature." (PMID 25187831, 2014).
reflux esophagitis (3 papers, 2012 to 2024). "Ustaoglu’s study revealed an upregulation of nerve growth factor (NGF) expression in mast cells infiltrating the esophageal mucosa of patients suffering from reflux esophagitis." (PMID 39139634, 2024). "Our findings suggest that mucosal mast cells are also key players in heartburn transmission, given their increased expression of NGF which likely leads to sprouting of nociceptive nerve endings, thus increasing activation of sensory pathways." (PMID 38098488, 2023). "The patient with very high serum NGF level was found to have multiple medical diseases including peptic ulcer, chronic hepatitis, thyrotoxicosis, reflux esophagitis and lumbar spondylosis." (PMID 23028581, 2012).
rheumatic diseases (3 papers, 2018 to 2024). "Indeed, increased levels of NGF are found in rheumatic diseases and anti-NGF/TrkA therapy reduces arthritic pain in human and animal models." (PMID 30240782, 2018).
rhinitis (3 papers, 2005 to 2024). An inflammation of the mucous membrane lining the nose, usually associated with nasal discharge. "When allergens interact with IgE-receptors, a higher level of NGF is detected, suggesting that allergens induce the release of NTs in diseases such as asthma or rhinitis." (PMID 38534776, 2024). "After capsaicin challenge, the symptom scores for rhinitis had a strong, but unsurprising, correlation with an increase in NGF, because the nasal mucosa may have produced the factor being analyzed." (PMID 16002371, 2005).
small cell lung carcinoma (3 papers, 2022 to 2025). Small cell lung cancer (SCLC) is a highly aggressive malignant neoplasm, accounting for 10-15% of lung cancer cases, characterized byrapid growth, and early metastasis. "NGF inhibited the growth of small-cell lung carcinoma cells and repressed tumorigenic potential in nude mice." (PMID 35155573, 2022).
squamous cell carcinoma (3 papers, 2017 to 2021). A carcinoma arising from squamous epithelial cells. "Multivariate logistic regression modelling confirmed squamous cell carcinoma and adenocarcinoma were significantly associated with increased NGF h-score compared to benign pathology, when accounting for age and gender (OR 1.09 (1.06–1.12) and 1.08 (1.05–1.11) respectively, p < 0.001)." (PMID 29802376, 2018). "Squamous cell carcinoma and adenocarcinoma presented with a NGF h-score of 107 and 84 respectively (p < 0.0001)." (PMID 29802376, 2018). "NGF and proNGF were also increased in squamous cell carcinoma, as well as in adenocarcinoma (p < 0.0001)." (PMID 29802376, 2018). "This concomitant increased expression of both TrkA and its ligand NGF is suggestive of a NGF-mediated autocrine stimulation of squamous cell carcinoma." (PMID 29802376, 2018). "Squamous cell cancers secrete high levels of nerve growth factor (NGF)." (PMID 28690839, 2017).
staphylococcus aureus infection (3 papers, 2018 to 2025). An infectious process in which the bacteria Staphylococcus aureus is present. "The similarity in symptoms between patients with TRKA variants and our patients with a Plec variant suggests that Staphylococcus aureus infection in our patients also involves NGF-TRKA signaling." (PMID 38928066, 2024). "It has been observed that patients with impaired nerve growth factor (NGF)-tropomyosin receptor kinase A (TRKA) signaling are more susceptible to Staphylococcus aureus infection." (PMID 38928066, 2024).
Tinnitus (3 papers, 2017 to 2024). Tinnitus is an auditory perception that can be described as the experience of sound, in the ear or in the head, in the absence of external acoustic stimulation. "Remarkably, the growth factors NGF, NTF3, and FGF2 are only present in the pathways associated with tinnitus." (PMID 39062188, 2024). "It is important to note that in the tinnitus group there were also close associations of BDNF to NGFR and of NGF to NTRK1." (PMID 37736859, 2023). "In summary, BDNF and NGF interact in tinnitus with NTRK1/NGFR in a competitive, modulatory manner influencing development, degeneration, and regeneration of neuronal and non-neuronal tissue." (PMID 37736859, 2023). "Because NGF is detectable in physiologically effective amounts in the blood and NTRK1 receptors are expressed in the spiral ganglion, therapeutic trials have been undertaken for sensorineural hearing loss and tinnitus." (PMID 37736859, 2023). "Highly significant GO terms in CN in tinnitus were “RNA polymerase II transcription factor complex”, “late endosome”, cellular response to cadmium ion”, “cellular response to reactive oxygen species”, and “nerve growth factor signaling pathway”, indicating changes in vesicle and cell homeostasis." (PMID 39062188, 2024). "The key proteins of tinnitus differ from those assigned to PoS and AcouStim not only in the proteins themselves but also by the observation that the HDPs BDNF and NGF show HSIs with NGFR and NTRK1 at approximately the same level of interaction." (PMID 37736859, 2023). "BDNF and NGF, in their interaction with NTRK1/NGFR, are involved in cell growth, survival, and regeneration, with the consequence of the changes in synaptic transmission connected with tinnitus." (PMID 37736859, 2023).
vitamin B12 deficiency (3 papers, 2013 to 2019). A disease characterized by low serum levels of vitamin B12, either inherited or acquired. "A series of our animal studies have demonstrated reduced levels of neurotrophins like NGF (nerve growth factor) and BDNF in the brain as a consequence of vitamin B12 deficiency." (PMID 26809263, 2016).